EGFR (epidermal growth factor receptor)
Diseases named in the same sentence as EGFR in open-access papers (continued):
Sharing a sentence is not in itself a finding about the gene and the disease.
breast carcinoma (continued). "EGFR is a hall-mark of basal like breast cancer and has repeatedly been presented as a key player promoting EMT." (PMID 32300922, 2020). "Among the components of TNuF, n-3 PUFA has been proven to decrease the phosphorylation of EGFR in human breast cancer cells." (PMID 32872195, 2020). "Epidermal growth factor receptor (EGFR) is also an important marker to look at in cancer, especially breast cancer, as it can affect the differentiation and proliferation of cancer cells." (PMID 32372949, 2020). "In this study, we examined the molecular mechanism through which CD99 agonist ligand suppresses ligand-induced dimerization and internalization of EGFR in breast carcinoma cells." (PMID 33050232, 2020). "EGFR is a therapeutic target in basal-like breast cancer, ErbB-2 is a target in the ErbB-2 overexpressing breast cancers, and ER-α is a target to hormone therapy in luminal breast cancers." (PMID 32466213, 2020). "In general, human epidermal growth factor receptor 1 (EGFR or erbB1) sensing in the breast cancer cells is directly achieved by RM, which is responsible for HER2+ overexpression." (PMID 32992464, 2020). "Network analysis further reveals that Prunella vulgaris L. produces therapeutic effects on breast cancer by inhibiting key targets in the ErbB signaling pathway and estrogen signaling pathways, such as AKT1, EGFR, and MYC." (PMID 32978480, 2020). "We demonstrate that PGRMC1 mediates progression of breast cancer cells potentially by altering cholesterol and lipid metabolism and activating key drivers of tumor progression in breast cancer, namely ERα expression and activation, as well as EGFR signaling." (PMID 32660617, 2020). "For example, the association between age and tumor grade, Ki-67 markers, apoptosis index, EGFR expression and erbB-2 expression has been reported in breast cancer." (PMID 32819307, 2020). "Breast cancer cell EVs have been shown to promote monocyte survival through EGFR transfer and subsequent activation of the MAPK pathway." (PMID 33143170, 2020). "This positive correlation is particularly evident in ERα+ and ERα- breast cancer patient samples, cancer cell types known to have elevated EGFR and IGF1R expression." (PMID 32340151, 2020). "Whereas endocrine therapy induces suppression of amphiregulin in responsive cells, the activation of an amphiregulin/EGFR autocrine loop has been proposed to drive endocrine-resistant phenotypes in breast cancer." (PMID 33086721, 2020). "In breast cancer, studies have demonstrated that gefitinib treatment induces EGFR translocation to the mitochondria." (PMID 31936895, 2020). "Evidence is emerging that tumour-derived EVs can have an immune-modulating effect, mediated through the EGFR, in both lung and breast cancer." (PMID 33143170, 2020). "In breast cancer, tumour-derived EVs promoted monocyte survival, in a pro-inflammatory environment, through EGFR." (PMID 33143170, 2020). "The anti-EGFR RNA aptamer (EGFRapt) has been reported to specifically bind EGFR on the surface of MDA-MB-231 breast cancer cells." (PMID 32080195, 2020). "Additionally, it has been proposed that glucocorticoids may promote breast cancer metastasis through upregulation of pathways associated with metastasis such as epithelial mesenchymal transition, glucose metabolism, and epidermal growth factor receptor signalling." (PMID 32565802, 2020). "In oestrogen receptor-α negative (ERα-) and positive (ERα+) breast cancers, the activation of CB2R by JWH-015 reduced breast cancer cell survival via blocking of the EGFR and insulin-like growth factor-1 receptor (IGF1R) pathways." (PMID 32340151, 2020). "Rates of positive and strongly positive EGFR expression in breast cancer tissues were 52.0% (204/392) and 32.4% (127/392), respectively." (PMID 33313320, 2020). "We engineered BT20 and MDA-MB-468 (human EGFR+ breast cancer cell lines) cells with control shRNA (targeted to firefly luciferase) or shRNA targeted to HUNK (HUNK shRNA1 and shRNA2)." (PMID 31597954, 2020).
breast carcinoma (continued). "Current research shows that EGFR is highly expressed in a variety of epithelial tumors, especially in liver cancer, colorectal cancer, breast cancer and so on, and its expression level is closely related to tumor metastasis and prognosis." (PMID 33055358, 2020). "This was confirmed by measuring the expression levels of three different surface markers, HER2, EGFR, and EpCAM, expressed on breast cancer cells, by immunofluorescence analysis." (PMID 33659239, 2020). "Among the reversible inhibitors, erlotinib and gefitinib are currently FDA-approved for the treatment of NSCLC harboring exon-19 deletions and activating EGFR mutations, and lapatinib is approved for metastatic HER2+ breast cancer." (PMID 32366937, 2020). "A pronounced increase of FABP5 was also observed in breast cancer, and molecular analyses showed a close correlation between the chaperone levels with activation of the epidermal growth factor receptor (EGFR) signalling pathway." (PMID 32856199, 2020). "Together these EVs delivered let-7a to EGFR expressing xenograft breast cancer cells in RAG2−/− mice, eliciting a significant (P < 0.05) ~60% reduction in tumour size following weekly administration of GE11+, let-7a+ EVs for four weeks." (PMID 33228060, 2020). "E2β can also activate the epidermal growth factor receptor (EGFR) via the signaling of the lipid kinase sphingosine kinase-1 in breast cancer cells." (PMID 32570961, 2020). "In summary, these result show that in multiple HER2+ and/or EGFR+ breast cancer cell lines EGF selectively enables and/or potentiates activation of a subset of critical TGFβ-SMAD inducible invasion/migration-associated genes." (PMID 32350443, 2020). "Upon culture of CCSCs in breast cancer differential media these cells showed changes in the expression of cell surface markers such as Her2 and EGFR (beside CD133) suggesting their differentiation into Her2+ breast cancer." (PMID 32670883, 2020). "Though KLF4 and EGFR are both widely studied in breast cancer, this is the first report linking their activities in this disease." (PMID 32552913, 2020). "To verify the reliability of obtained targets in network pharmacology analysis, we have conducted western blot analysis for ER and EGFR protein expression to confirm signaling pathway in breast cancer effects of the CP." (PMID 33057155, 2020). "ERBB2 β3‐αC deletions (ΔLRENT) were only detected in breast cancers, which were sensitive to EGFR/ERBB2 inhibitor neratinib and resistant to lapatinib." (PMID 32757330, 2020). "Reverse LOX-mediated regulation of EGFR cell surface availability appears to be specific to primary and metastatic breast cancer cell lines." (PMID 32708046, 2020). "Intravenously injected EV successfully deliver their loaded let-7a miRNA to EGFR-expressing breast cancer tissues in RAG2–/–mice." (PMID 32942702, 2020). "EGFRvIII is a constitutively activated mutant variant of EGFR that is found in glioblastoma multiforme (GBM), breast cancer, NSCLC and HNSCC." (PMID 33143170, 2020). "Our group recently provided evidence that supports the conclusion that HUNK is a metastasis promoting factor by showing that HUNK regulates breast cancer metastasis through phosphorylation of EGFR." (PMID 32676513, 2020). "Here, we studied the potential role of miR-125a-3p as a modulator of the EGFR/HER2 pathway in basal-like breast cancer." (PMID 32185126, 2020). "AG-205 (PGRMC1 inhibitor) treatment decreased both total and phosphorylated EGFR leading to a decrease in breast cancer cell proliferation." (PMID 32867363, 2020). "Further, activation of the EGFR‐CAR NK cells significantly inhibited the progression of breast cancer in vitro and in vivo." (PMID 32592435, 2020). "A role of alcohol has been well recognized in initiation and progression of breast cancer, presumably via multiple cellular and molecular mechanisms, including the EGFR/ErbB2 pathways." (PMID 31605532, 2020).
breast carcinoma (continued). "To further confirm our overall observations, we performed an analysis using a TMA containing samples from triple-negative breast cancer patients with stage I–III breast cancers, to analyze the levels of pT654 EGFR throughout different stages of disease." (PMID 31597954, 2020). "Let‐7a, a tumor suppressor miRNA, were delivered by exosomes to inhibit EGFR in breast cancer xenografts." (PMID 32618144, 2020). "Further, positive correlation between mPRα, p-AKT and EGFR levels have been described in breast cancer cells." (PMID 32867363, 2020). "Here, we demonstrate that melittin alone selectively targets HER2- and EGFR-overexpressing breast cancer cells." (PMID 32923684, 2020). "Among the differentially expressed glycoproteins, levels of bisecting GlcNAc on EGFR were significantly decreased in breast cancer cells, confirmed by immunostaining and immunoprecipitation." (PMID 32612952, 2020). "Lapatinib is a dual inhibitor targeting both HER2 and EGFR that has an anti-cancer effect on HER2-positive breast cancer by inhibiting MAPK/Erk1/2 and PI3K/Akt downstream pathways." (PMID 32942617, 2020). "The fibroblast growth factor receptor (FGFR) is suggested to have crosstalk with the EGFR in cancer cells, such as breast cancer as well as normal development such as skeletogenesis." (PMID 33092268, 2020). "Despite different levels of EGFR expression, these two breast carcinomas were similarly affected by EGFR ligands and CD99 agonists." (PMID 33050232, 2020). "The present study investigated the prognostic value of EGFR and EGFR ligands in the serum of 311 patients with early-stage breast cancer and demonstrated significantly shorter survival in patients with low pretreatment levels of either S-EGFR or S-HBEGF." (PMID 33024132, 2020). "Another study found the NRG1/EGFR interaction to be critical for the promotion of proliferation in breast cancer cells." (PMID 32552913, 2020). "EGFR signaling is known to be associated with many different solid tumor types including colon cancer, non-small cell lung cancer (NSCLC), breast cancer, renal cancer, head and neck cancer, and glioma 49-51." (PMID 32742459, 2020). "Analyses using an 855-patient breast cancer gene expression dataset identified that both EGFR and BIRC5 have significantly higher expression levels in basal-like patient tumors compared to those of other subtypes." (PMID 32001757, 2020). "We found that STU treatment of animals orthotopically transplanted with 4T1 cells reduced the phosphorylation of EGFR at T654 in primary mammary tumors, which corresponded to a decrease in EGFR expression and lung metastases." (PMID 31597954, 2020). "Pathway analysis also indicated that Prunella vulgaris L. exerts anti-breast cancer effects by inhibiting key targets in the estrogen pathway and ErbB pathways, such as AKT1, EGFR, and MYC." (PMID 32978480, 2020). "Taken all together, our results suggest that pharmacological inhibition of HUNK impairs the phosphorylation of EGFR at T654 in primary mammary tumors and consequently, impairs metastasis." (PMID 31597954, 2020). "According to our data, allosteric binders enhance EGFR degradation, which can largely compensate for weak inhibition of the catalytic site in breast cancer cells." (PMID 31374910, 2019). "In breast cancer, K19 was shown to be critical for the proper activation of signaling pathways involving receptor tyrosine kinase epidermal growth factor receptor (EGFR) family members." (PMID 31126068, 2019). "The epidermal growth factor receptor (EGFR) activation is a common and important event in the pathogenesis and progression of breast cancer." (PMID 30646517, 2019).
breast carcinoma (continued). "In the same type of tumor cells (ESCC, NSCLC, breast cancer), the EGFR‐overexpressing cancer cells were more sensitive to LR004‐VC‐MMAE than the EGFR low‐expressing cells, in terms of the IC50 values." (PMID 30372581, 2019). "Lapatinib is a clinically approved drug which targets ERBB2 and EGFR in the treatment of breast cancer." (PMID 31645597, 2019). "Our group also identified co-expression of GLI1 and two GLI1 targets, EGFR and SNAI1, to be associated with worse disease-free survival in HR breast cancer." (PMID 31394751, 2019). "Binding of epidermal growth factor (EGF) to epidermal growth factor receptor (EGFR) leaded to the phosphorylation of CREB1 which resulted in a series of genes expression correlated with the progression of breast cancer." (PMID 31754343, 2019). "YBX1 has been reported to enhance EGFR transcription by directly binding to its promoter in breast cancer cells and chordoma cells." (PMID 31358880, 2019). "CNAs have been extensively investigated in many cancers, and some known biomarkers were identified though these studies (e.g., EGFR amplification in non-small cell lung cancer; erb-b2 amplification in breast cancer)." (PMID 31159251, 2019). "In this study, we demonstrate neratinib as the inhibitor of MST1, a previously unappreciated activity alongside the dual inhibition of HER2/EGFR that drives its clinical utility in breast cancer." (PMID 31676778, 2019). "In the current study, XAN, BER, ANG, PSO, IMP were selected on the basis of their best docking scores against breast cancer which was further validated by specific in-vitro assays of ERα, EGFR and mTOR." (PMID 31673107, 2019). "HER2 is overexpressed in 15–25% of breast cancer (BC), whereas EGFR is found in 15–20% of BC and in up to 60% of basal triple-negative BC." (PMID 31146485, 2019). "EGFR protein levels are higher in TNBC than the other subtypes of breast cancers, and the combination of a monoclonal antibody targeting EGFR with cisplatin extends both disease-free and overall survival." (PMID 31406104, 2019). "In this study, we demonstrate the in vitro and in vivo growth-inhibitory activity of an ER-resident E3 ubiquitin ligase, CGRRF1, in breast cancer and identify EGFR as its ubiquitin ligase substrate through unbiased RPPA analysis." (PMID 31801577, 2019). "We found the trend of EGFR expression was the same as PN-1 expression in cell lines and breast cancer tissues." (PMID 31501409, 2019). "For instance, a dual-ligand nanoparticle targeting EGFR and αvβ3 integrin can achieve a nearly 2-fold higher deposition into breast cancer metastasis in the lungs than its single-ligand nanoparticle counterparts." (PMID 31356633, 2019). "Epidermal growth factor receptor (EGFR) and proto-oncogene tyrosine-protein kinase Src (c-Src) are critical components of the signaling pathways that are associated with breast cancer." (PMID 31430896, 2019). "A recent report demonstrated the direct tumoristatic effects of cetuximab and trastuzumab on canine mammary carcinoma cells expressing EGFR and HER-2." (PMID 31610784, 2019). "Protein tyrosine phosphatase 1B (PTP1B) is involved in the dephosphorylation process of tyrosine kinases responsible for breast cancer development, i.e., HER1/EGFR, Src, JAK, as well as of signal transducer and activator of transcription (STAT)." (PMID 31652764, 2019). "EGFR is an important factor that enhances the malignancy of drug-resistant breast cancer cells and mediates the resistance of the prostate cancer cells to chemotherapeutic drugs." (PMID 31215501, 2019).
breast carcinoma (continued). "In contrast with several above-mentioned MPs (e.g., CD44, EGFR/ERBB2, and APP) that have been well studied, the interacting partners and pathways associated with CHRNA9 in breast cancer remain to be elucidated." (PMID 31311925, 2019). "Based on promising preclinical studies, our group conducted a Phase 1 clinical trial of 111In-DTPA-hEGF in 16 patients with metastatic EGFR-positive breast cancer administered 370–2220 MBq (0.25 mg)." (PMID 31659527, 2019). "EGFR signaling has been known to decrease 3H-Thymidine incorporation in EGF treated breast cancer cells, including SKBR3 cells." (PMID 30736768, 2019). "In the mice intracranially pre-inoculated with EGFR-expressing breast cancer cells, intratumoral administration of EGFR-CAR-transduced NK-92 cells mitigated tumor growth compared to mock NK cells." (PMID 30805309, 2019). "FAM83A and B proteins have been identified as possible key regulators in the EGFR pathway in breast cancer cells, leading to the development of resistance to TKIs." (PMID 31083571, 2019). "A better understanding of the GPER, its role in breast cancer, and the interactions with the ER and epidermal growth factor receptor will be beneficial for the disease management and prevention in the future." (PMID 30646517, 2019). "Luminal breast cancer can be identified by three major parameters named as estrogen receptor (ER), progesterone receptor (PR) and human epidermal growth factor receptor (HER-2)." (PMID 31480430, 2019). "Above achievements inspired us to use these target medicine to treat breast cancer with high EGFR mutant rates." (PMID 31171012, 2019). "This mutation occurs in about 30% of human breast cancers, where it leads to gain-of-function mutations in gene PIK3CA that activate the PI3K-AKT-signaling pathway constantly, thereby uncoupling the EGFR response from AKT signaling." (PMID 31438847, 2019). "In this study, we thus evaluated how EGFR activation influences breast cancer cell glucose metabolism and proliferation." (PMID 31532771, 2019). "The epidermal growth factor receptor (EGFR) is a potential oncogene in breast cancer, with the repression of EGFR amplification reported to have antiproliferative benefits in breast cancer." (PMID 30769862, 2019). "ACK1 can enhance the migration and invasion ability of breast cancer cells by strengthening the EGFR signaling pathway." (PMID 31772931, 2019). "For example, 111In-labelled block copolymer micelles (BCMs) modified with EGF to target EGFR-positive breast cancer cells were assembled by incorporating a DTPA-polyethylene glycol (PEG)-b-polycaprolactone (PCL) block polymer into these micelles." (PMID 31659527, 2019). "It is reported that EGFR inhibition decreased the rate of brain metastases in human DMA‐MB‐231 breast cancer cell lines." (PMID 31144459, 2019). "To further investigate the hindering effects of iEFs on EGF-promoted migration of breast cancer cells, we blocked Akt signaling, an important downstream effector of EGFR phosphorylation." (PMID 31428691, 2019). "This study focused on the screening of small-molecule inhibitors that target the EGFR/Eps8 complex in breast cancer and non-small cell lung cancer (NSCLC)." (PMID 31118055, 2019). "The positive correlation between EGFR and PN-1 expression levels was further illustrated in 70-paired breast cancer tissues from the hospital and 1104 breast cancer tissues from StarBase database." (PMID 31501409, 2019). "Expression of EGFR is activated in many malignancies such as breast cancer, prostate cancer and gliomas and stimulates growth and differentiation of neurons." (PMID 30726272, 2019). "More importantly, EGFR depletion/AJAP1 knocked down promoted the progression of breast cancer by regulating the activity of β-catenin nuclear transactivation." (PMID 31171012, 2019).